SREBF1 (sterol regulatory element binding transcription factor 1)
Description:
[Sterol regulatory element-binding protein 1]: Precursor of the transcription factor form (Processed sterol regulatory element-binding protein 1), which is embedded in the endoplasmic reticulum membrane. Low sterol concentrations promote processing of this form, releasing the transcription factor form that translocates into the nucleus and activates transcription of genes involved in cholesterol biosynthesis and lipid homeostasis (By similarity). [Processed sterol regulatory element-binding protein 1]: Key transcription factor that regulates expression of genes involved in cholesterol biosynthesis and lipid homeostasis. Binds to the sterol regulatory element 1 (SRE-1) (5'-ATCACCCCAC-3'). Has dual sequence specificity binding to both an E-box motif (5'-ATCACGTGA-3') and to SRE-1 (5'-ATCACCCCAC-3'). [Isoform SREBP-1A]: Isoform expressed only in select tissues, which has higher transcriptional activity compared to SREBP-1C (By similarity). Able to stimulate both lipogenic and cholesterogenic gene expression. Has a role in the nutritional regulation of fatty acids and triglycerides in lipogenic organs such as the liver (By similarity). Required for innate immune response in macrophages by regulating lipid metabolism (By similarity). [Isoform SREBP-1C]: Predominant isoform expressed in most tissues, which has weaker transcriptional activity compared to isoform SREBP-1A (By similarity). Primarily controls expression of lipogenic gene. Strongly activates global lipid synthesis in rapidly growing cells (By similarity). [Isoform SREBP-1aDelta]: The absence of Golgi proteolytic processing requirement makes this isoform constitutively active in transactivation of lipogenic gene promoters. [Isoform SREBP-1cDelta]: The absence of Golgi proteolytic processing requirement makes this isoform constitutively active in transactivation of lipogenic gene promoters.
Synonyms: bHLHd1; SREBP1; SREBP-1c; SREBP1a; HMD; IFAP2
Tractability: Small molecule: a high-quality ligand is known. Antibody: UniProt predicts a signal peptide or a membrane-spanning region. PROTAC: UniProt records ubiquitination sites on it; ubiquitination databases record sites on it; a small molecule that binds it is known.
Target class: Transcription factor
Safety:
Unwanted effects reported when the protein is acted on. In parentheses: how it was acted on, where the effect was seen, and who reports it.
Increased, Liver Steatosis (AOP-Wiki: activation; AOP-Wiki: inhibition)
N/A, Liver Steatosis (activation; source: AOP-Wiki)
increase in total cholesterol levels (source: ClinPGx)
increase or decrease in total cholesterol levels (source: ClinPGx)
Gene: Protein-coding gene on chromosome 17 (17,810,399 to 17,837,030, reverse strand). Ensembl gene ENSG00000072310.
Subcellular location: Endoplasmic reticulum membrane (Sterol regulatory element-binding protein 1); Golgi apparatus membrane; Cytoplasmic vesicle, COPII-coated vesicle membrane; Nucleus (Processed sterol regulatory element-binding protein 1); Nucleus (Isoform SREBP-1aDelta); Nucleus (Isoform SREBP-1cDelta)
Subcellular location (Human Protein Atlas): Nucleoplasm
Pathways (Reactome):
Metabolism: Activation of gene expression by SREBF (SREBP); PPARA activates gene expression; Regulation of cholesterol biosynthesis by SREBP (SREBF); Zymostenol biosynthesis via lathosterol (Kandutsch-Russell pathway)
Circadian clock: RORA,B,C and NR1D1 (REV-ERBA) regulate gene expression
Developmental Biology: Transcriptional regulation of white adipocyte differentiation
Gene expression (Transcription): FOXO-mediated transcription of oxidative stress, metabolic and neuronal genes
Signal Transduction: NR1H2 & NR1H3 regulate gene expression linked to lipogenesis
Gene Ontology:
Molecular function: DNA-binding transcription activator activity, RNA polymerase II-specific; DNA-binding transcription factor activity; DNA-binding transcription factor activity, RNA polymerase II-specific; nuclear receptor activity; protein binding; RNA polymerase II transcription regulatory region sequence-specific DNA binding; sequence-specific double-stranded DNA binding; sterol response element binding; transcription coregulator binding; DNA binding; RNA polymerase II cis-regulatory region sequence-specific DNA binding; chromatin binding; protein dimerization activity; protein kinase binding; protein-containing complex binding; sequence-specific DNA binding
Biological process: cholesterol metabolic process; lipid biosynthetic process; negative regulation of triglyceride metabolic process; positive regulation of cholesterol biosynthetic process; positive regulation of miRNA transcription; positive regulation of transcription by RNA polymerase II; regulation of establishment of protein localization to mitochondrion; regulation of mitophagy; regulation of protein stability; regulation of transcription by RNA polymerase II; SREBP signaling pathway; cellular response to starvation; lipid metabolic process; positive regulation of triglyceride biosynthetic process; cellular response to fatty acid; cellular response to insulin stimulus; circadian rhythm; intracellular receptor signaling pathway; lung development; positive regulation of DNA-templated transcription; response to cAMP; response to ethanol; response to fatty acid; response to food; response to fructose; and 7 more
Cellular component: nucleoplasm; nucleus; SREBP-SCAP complex; chromatin; cytoplasm; cytosol; endoplasmic reticulum membrane; Golgi apparatus; Golgi membrane; nuclear envelope; SREBP-SCAP-Insig complex; ER to Golgi transport vesicle membrane; membrane; protein-containing complex
Genetic constraint (gnomAD): Loss-of-function variants: 45 observed, 87.14 expected, observed/expected ratio (o/e) 0.52, 90% interval 0.41 to 0.66. The upper end of that interval is the gene's LOEUF score, 0.66, which puts it in group 2 of 6, group 1 being the genes least tolerant of losing a copy. Missense variants: 1,324 observed, 1,441.2 expected, observed/expected ratio (o/e) 0.92, 90% interval 0.88 to 0.96. Synonymous variants: 657 observed, 625.38 expected, observed/expected ratio (o/e) 1.05, 90% interval 0.99 to 1.12.
Homologues: Orthologues: chimpanzee SREBF1 (99% identical), macaque SREBF1 (97% identical), dog SREBF1 (88% identical), guinea pig SREBF1 (86% identical), pig SREBF1 (85% identical), rat Srebf1 (80% identical), mouse Srebf1 (80% identical), tropical clawed frog srebf1 (58% identical), zebrafish srebf1 (43% identical). Paralogues in human: SREBF2 (43% identical), USF2 (8% identical), USF1 (7% identical).
Diseases named in the same sentence as SREBF1 in open-access papers:
SREBF1 is named in the same sentence as 295 diseases in open-access papers, as found by Europe PMC text mining. Sharing a sentence is not in itself a finding about the gene and the disease. The quoted sentences say what the papers report.
Hepatic steatosis (651 papers, 2009 to 2026). Steatosis is a term used to denote lipid accumulation within hepatocytes. "Intriguingly, ovariectomized (OVX) HFD-fed females exhibited obesity, glucose intolerance, insulin resistance, and moderate hepatic steatosis, linked to upregulated hepatic lipogenic (Srebf1, Scd1), β-oxidative (Cpt1a), and ER stress (Hspa5, Hyou1) genes." (PMID 40475995, 2025). "In animal and cell models of NAFLD, MALAT1 expression was higher, and this upregulation caused an increase of Srebf1 mRNA and protein expression and promoted hepatic steatosis." (PMID 35052690, 2021). "In case of down-regulated Gli1 and Gli3, prominent lipogenic transcription factors (e.g. Ppara/g, Srebf1) are up-regulated and influence an entire network of several genes associated with lipid metabolism which finally ends up with hepatic steatosis." (PMID 27185526, 2016). "Overactivation of Srebf1 leads to excessive production of fatty acids and triglycerides in the liver, directly contributing to abnormal fat accumulation in the liver, a hallmark of fatty liver disease." (PMID 41450877, 2025). "We found that miR-21a-5p expression was decreased in PFD group, as well as, Srebf1 and Tgfb1. miR-21a-5p hepatic diminution has been associated with improved glucose tolerance and insulin sensitivity, in addition to prevent hepatic steatosis and fatty acid absorption." (PMID 34083664, 2021). "Moreover, hesperidin prevented hepatic steatosis in western diet-fed rats by preventing the upregulation of lipogenesis-related genes Srebf1, and Scd1 caused by Western diet and the downregulation of Pparα and Cpt1a expression and CPT1a protein levels." (PMID 32785059, 2020). "BPA-induced hepatic steatosis in mouse/HepG2 models correlated with miR-192 downregulation and SREBF1-mediated lipogenic activation." (PMID 40475995, 2025). "Pparα agonists have also been reported to inhibit Srebf1 expression and Pparα activation reduces the development of hepatic steatosis." (PMID 39537943, 2024). "SID1 transmembrane family member 2 (SIDT2) deficiency induces ER stress and results in hepatic steatosis by upregulating SREBP1, sterol regulatory element binding transcription factor 1 (SREBF1) and fatty acid biosynthesis." (PMID 38310315, 2024). "Afriplex GRTTM reduced hepatic steatosis in oleic acid induced C3A liver cells by modulating SREBF1, ChREBP and IRS-1 gene expression." (PMID 38630788, 2024). "Inhibition of FTO by entacapone decreased the expression of SREBF1, ChREBP, and downstream lipogenic genes, ameliorating liver steatosis in HFD-fed mice." (PMID 36352530, 2023). "Increased activation of LXRα and expression of Srebf1 result in increased lipid synthesis and triglyceride metabolism and in hepatic steatosis." (PMID 33104749, 2020). "Inhibition of ER stress in obese rodents decreases SREBF1 activation and lipogenesis and improves markedly hepatic steatosis." (PMID 31680967, 2019). "In humans, the hepatic expression of SREBF1, as well as its target lipogenic genes, varies according to the severity of fatty liver." (PMID 30103390, 2018). "Studies have linked hepatic steatosis to ER stress-induced sterol regulatory element-binding protein 1c (SREBP-1c; also known as SREBF1) expression and activation, and we observed significant SREBP-1c upregulation after TG-FA early treatment." (PMID 30254132, 2018). "Non-sterol ligands lack the biophysical properties to arrest Srebf1 maturation, and their administration is marked by hepatic steatosis and hypertriglyceridemia." (PMID 28536535, 2017). "The hepatic overexpression of Dgat2, which catalyzes the final step of triglyceride synthesis, led to hepatic steatosis in mice, and liver-specific disruption of Pparγ or Srebf1 protected mice against hepatic steatosis." (PMID 27213439, 2016). "We observed repression of elongases V (ELOVL5) that in turn regulates sterol regulatory element binding protein 1c (SREBF1) to induce hepatic steatosis." (PMID 25470483, 2014).
Hepatic steatosis (continued). "Using miR-33−/−Srebf1+/− mice, we demonstrate that SREBP-1 is a target of miR-33 and that the mechanisms leading to obesity and liver steatosis in miR-33−/− mice involve enhanced expression of SREBP-1." (PMID 24300912, 2013). "This includes for example the regulation of SIRT1, a protein known to activate PPARG and SREBF1, which contributes to hepatic steatosis in obesity upon ubiquitination and proteasomal stimulation of its degradation." (PMID 24324835, 2013). "The downregulation of FASN and SREBF1 is involved in hepatic steatosis." (PMID 38992651, 2024). "miR-33-5p plays an important role in Srebf1 mRNA decay during the development of hepatic steatosis." (PMID 36759348, 2023). "SREBF1/SREBP-1c was activated under an HFD-induced liver steatosis model." (PMID 37244925, 2023). "However, SR treatment attenuated HFD-induced hepatic steatosis by suppressing TG contents and the expression of fatty acid transport- and lipogenesis-related genes including Fabp1, Fabp4, Slc27a5, Pparg, Mlxipl, Srebf1, Srebf2, Fas, Dgat1, and Dgat2." (PMID 35454963, 2022). "Among genes related to NAFLD, both m6A peaks and mRNA levels of Srebp1 (also named Srebf1) were significantly decreased, which further indicates that lipogenesis likely contributes little to fatty liver observed in Mettl3-HKO mice." (PMID 34893641, 2021). "Specifically in the liver, Chikka and colleagues suggest that CHOP is a suppressor of key regulators of lipid metabolism like Cebpa, Ppara, and Srebf1, and demonstrate that CHOP-deficient mice tend to develop hepatic steatosis in response to bortezomib-induced ER stress." (PMID 33210603, 2020). "Several studies on mice with hepatic steatosis have shown that several transcription factors and components of the triacylglycerol metabolism such as PPARγ (Pparg), fatty acid synthetase (Fasn), SREBP-1c (Srebf1) and stearoyl-coenzyme A desaturase 1 (Scd1) are increasingly expressed in the liver." (PMID 28030540, 2016). "Therefore, the interaction between H19 and miR-130a to regulate Srebf1 could be the primary driver for hepatic steatosis." (PMID 35052690, 2021). "Moreover, obese animals showed higher (P < 0.05) transcript levels of the lipogenic genes Pparg, Srebf1, Mogat2 and Dgat1 as well as a moderate-to-severe hepatic steatosis evidenced by the staining of the lipid droplet-coating protein adipophilin in liver sections." (PMID 28008992, 2016). "Hepatic steatosis was reversed in miR-33−/−Srebf1+/− mice compared with that in miR-33−/−Srebf1+/+ mice in both macro- and microscopic images and the liver triglyceride content of these mice was almost the same as that of miR-33+/+Srebf1+/+ and miR-33+/+Srebf1+/− mice." (PMID 24300912, 2013). "Oxymatrine inhibited the transcription factor sterol regulatory element binding transcription factor 1 (SREBF1) and Peroxisome Proliferator-activated Receptor α (PPARα) and suppressed hepatic steatosis in non-alcoholic fatty liver disease." (PMID 37600712, 2023). "The miR-130a inhibits hepatic steatosis by suppressing the expression of NAFLD-related genes, including Pparg, Srebf1, Scd1, Acc1, and Fasn." (PMID 35052690, 2021). "This CAM protein suppresses the mTOR/SREBF1 pathway and activates the PI3K/AKT pathway, alleviating hyperglycemia and hepatic steatosis." (PMID 35052690, 2021). "The findings lead to introduction of an informative biomarker panel including INS, PPARA, LEP, SREBF1, and ALB proteins related to the fatty liver disease." (PMID 28224024, 2016). "Since Srebf1 is known to link oxidative stress to hepatic steatosis, alleviation of oxidative stress by TUDCA likely decreases the expression of Srebf1 and subsequently reduces de novo lipogenesis." (PMID 21079772, 2010). "In contrast, network members promoting development of hepatic steatosis, such as PPARγ, SCD, SREBF1, ACOX1, CIDEC and CFD (adipsin) are repressed during early phase and induced during the late phase of hepatic response to HF diets." (PMID 19680557, 2009).
Hepatic steatosis (continued). "In rodents, PFAAs-induced liver steatosis and toxicity have been mainly attributed to PPARα, which activation leads to increased expression of genes involved in FAO, lipogenesis (Srebf1, sterol regulatory element-binding transcription factor 1; Fasn, fatty acid synthase), and lipid uptake (Cd36)." (PMID 37242221, 2023). "INS, PPARA, LEP, SREBF1, and ALB are the introduced biomarker panel for fatty liver disease." (PMID 28224024, 2016). "The absence of OPN reversed HFD-induced fatty liver, as shown by the reduction of lipogenic gene expression of Srebf1, Mogat1 and Dgat2 and TG accumulation in the liver." (PMID 24871103, 2014). "On the one hand, SREBF1 has been shown to be increased in fatty liver rather than NASH." (PMID 37263777, 2023). "In addition, some studies have shown that antibiotics reduce hepatic steatosis by inhibiting intestinal FXR, thereby downregulating the expression of sterol regulatory element-binding transcription factor 1 (SREBP1C) and cell death-inducing DFFA like effector A (CIDEA) in the liver." (PMID 36119048, 2022). "Thus, FGF19 and NGM282 appear to selectively modulate LXR signaling, upregulating canonical LXR target genes (Abcg5, Abcg8, Scarb1, Srebf1, Fasn, Scd1, Srebf2, and Scap) without inducing hepatic steatosis." (PMID 30679232, 2019). "However, hepatic steatosis was ameliorated, rather than increased, following FGF19 or NGM282 treatment of db/db mice, despite increases in Srebf1, Fasn, and Scd1 mRNA levels." (PMID 30679232, 2019).